SLC17A6 (solute carrier family 17 member 6)
Description:
Multifunctional transporter that transports L-glutamate as well as multiple ions such as chloride, proton, potassium, sodium and phosphate. At the synaptic vesicle membrane, mainly functions as a uniporter which transports preferentially L-glutamate but also, phosphate from the cytoplasm into synaptic vesicles at presynaptic nerve terminals of excitatory neural cells. The L-glutamate or phosphate uniporter activity is electrogenic and is driven by the proton electrochemical gradient, mainly by the electrical gradient established by the vacuolar H(+)-ATPase across the synaptic vesicle membrane. In addition, functions as a chloride channel that allows the chloride permeation through the synaptic vesicle membrane therefore affects the proton electrochemical gradient and promotes synaptic vesicles acidification (By similarity). Moreover, functions as a vesicular K(+)/H(+) antiport allowing to maintain the electrical gradient and to decrease chemical gradient and therefore sustain vesicular glutamate uptake (By similarity). The vesicular H(+)/H(+) antiport activity is electroneutral (By similarity). At the plasma membrane, following exocytosis, functions as a symporter of Na(+) and phosphate from the extracellular space to the cytoplasm allowing synaptic phosphate homeostasis regulation (Probable). The symporter activity is driven by an inside negative membrane potential and is electrogenic (Probable). Also involved in the regulation of retinal hyaloid vessel regression during postnatal development (By similarity). May also play a role in the endocrine glutamatergic system of other tissues such as pineal gland and pancreas (By similarity).
Synonyms: VGluT2; DNPI
Tractability: Antibody: UniProt places it where antibodies can reach, with high confidence; UniProt predicts a signal peptide or a membrane-spanning region; its Gene Ontology location is reachable by antibodies, with medium confidence. PROTAC: ubiquitination databases record sites on it; its protein half-life has been measured.
Gene: Protein-coding gene on chromosome 11 (22,338,381 to 22,379,503, forward strand). Ensembl gene ENSG00000091664.
Subcellular location: Cytoplasmic vesicle, secretory vesicle, synaptic vesicle membrane; Synapse, synaptosome; Cell membrane
Pathways (Reactome):
Transport of small molecules: SLC-mediated transport of neurotransmitters
Gene Ontology:
Molecular function: L-glutamate uniporter activity; chloride channel activity; L-glutamate transmembrane transporter activity; neurotransmitter transmembrane transporter activity; potassium:proton antiporter activity; sodium:phosphate symporter activity; secondary active transmembrane transporter activity; transmembrane transporter activity
Biological process: L-glutamate import; phosphate ion homeostasis; hyaloid vascular plexus regression; neurotransmitter loading into synaptic vesicle; neurotransmitter transport; phosphate ion transport; regulation of synapse structure or activity; sodium-dependent phosphate transport; synaptic transmission, glutamatergic; chloride transmembrane transport; L-glutamate transmembrane transport; potassium ion transmembrane transport; proton transmembrane transport; sodium ion transmembrane transport; transmembrane transport
Cellular component: synaptic vesicle membrane; excitatory synapse; neuron projection; plasma membrane; synapse
Genetic constraint (gnomAD): Loss-of-function variants: 28 observed, 57.47 expected, observed/expected ratio (o/e) 0.49, 90% interval 0.36 to 0.67. The upper end of that interval is the gene's LOEUF score, 0.67, which puts it in group 2 of 6, group 1 being the genes least tolerant of losing a copy. Missense variants: 522 observed, 688.66 expected, observed/expected ratio (o/e) 0.76, 90% interval 0.7 to 0.81. Synonymous variants: 245 observed, 240.19 expected, observed/expected ratio (o/e) 1.02, 90% interval 0.92 to 1.13.
Homologues: Orthologues: chimpanzee SLC17A6 (100% identical), macaque SLC17A6 (99% identical), dog SLC17A6 (99% identical), pig SLC17A6 (98% identical), rabbit SLC17A6 (98% identical), mouse Slc17a6 (97% identical), rat Slc17a6 (97% identical), guinea pig SLC17A6 (93% identical), tropical clawed frog slc17a6 (91% identical), zebrafish slc17a6a (86% identical), zebrafish slc17a6b (85% identical), Drosophila melanogaster VGlut (46% identical), and 28 more. Paralogues in human: SLC17A7 (74% identical), SLC17A8 (73% identical), SLC17A5 (34% identical), SLC17A4 (27% identical), SLC17A2 (26% identical), SLC17A3 (25% identical), SLC17A1 (24% identical), SLC17A9 (19% identical), SLC37A4 (16% identical), SLC37A1 (15% identical), SLC37A2 (15% identical), SLC37A3 (13% identical).
Diseases named in the same sentence as SLC17A6 in open-access papers:
SLC17A6 is named in the same sentence as 86 diseases in open-access papers, as found by Europe PMC text mining. Sharing a sentence is not in itself a finding about the gene and the disease. The quoted sentences say what the papers report.
schizophrenia (6 papers, 2016 to 2025). A major psychotic disorder characterized by abnormalities in the perception or expression of reality. "However, some rare genetic variants of the human VGLUT2/SLC17A6 gene have been identified in schizophrenia and severe alcoholism." (PMID 27699212, 2016).
Alzheimer disease (4 papers, 2012 to 2023). A progressive, neurodegenerative disease characterized by loss of function and death of nerve cells in several areas of the brain leading to loss of cognitive function such as memory and language.
cognitive decline (2 papers, 2012 to 2022). "Furthermore, loss of SLC17A6 is correlated with cognitive decline in AD." (PMID 35637434, 2022).
colon cancer (2 papers, 2023). "The exact roles of SLC17A6 in CMS4 subtype colon cancer warrant further investigation." (PMID 37404825, 2023).
-Aldrich syndrome (1 paper, 2023). "We found 14 common targets for this highlighted anxiogenic miRs, among them Solute carrier family 17 (vesicular glutamate transporter), member 6 (Slc17a6), Wiskott-Aldrich syndrome-like (Wasl), and Ataxin-1 (Atxn1) have a higher rank for interaction." (PMID 36979479, 2023).
Nicotine addiction (1 paper, 2025). "Among these, the TGF-beta signaling pathway, T cell receptor signaling pathway, and Nicotine addiction pathway were highly enriched (p < 0.01) enriched involving relevant genes (PITX2, ID4, BMP4, DLG1, IKBKB, ICOS, GRIA3, and SLC17A6)." (PMID 40496916, 2025).
tumor (2 papers, 2020 to 2022).
SLC17A6 also shares sentences with these, for which no sentence is quoted: Anxiety (17 papers); Obesity (10); Parkinson disease (10); depression (8); infection (8); Cognitive impairment (4); glaucoma (4); Hypoglycemia (4); Tinnitus (4); alcoholism (3); epilepsy (3); itch (3); memory impairment (3); channelopathy (2); dementia (2); dental pulp inflammation (2); diabetes (2); glial tumors (2); neuropathy (2); Parkinson's (2); psychiatric disorder (2); respiratory failure (2); status epilepticus (2); Stroke (2); absence seizures (1); age-related hearing loss (1); alcohol use disorder (1); Anorexia (1); apneic episodes (1); Ataxia (1).
A further 49 diseases each share a sentence with SLC17A6 in 1 paper.